MMP7 (matrix metallopeptidase 7)
Diseases named in the same sentence as MMP7 in open-access papers (continued):
Sharing a sentence is not in itself a finding about the gene and the disease.
lung cancer (continued). "Together, these results indicate that fibulin-5 suppresses MMP-7 expression and lung cancer invasion through ERK inhibition and GSK3β activation, which in turn prevents β-catenin accumulation and nuclear translocation." (PMID 25909283, 2015). "In summary, an increased expression of MMP-7 was found in the present meta-analysis to be strongly associated with advanced TNM stage, histologic grade, and aggressive LN metastasis in lung cancer patients." (PMID 25588786, 2015). "A few studies have reported that MMP-7 shows a great promise as a biomarker to assess lung cancer proliferation, differentiation and metastasis." (PMID 25588786, 2015). "MMP-7 overexpression is reported to be associated with the TNM stage, histologic grade and LN metastasis of lung cancer." (PMID 25588786, 2015). "We searched the databases PubMed, Embase, Web of Science, Cochrane Library, CISCOM, CINAHL, China BioMedicine (CBM) and China National Knowledge Infrastructure (CNKI) for scientific literature relevant to MMP-7 and lung cancer." (PMID 25588786, 2015). "Wnt1 is involved in the regulation of MMP-7 expression, and therefore, Wnt signaling pathway plays a significant role in the lung cancers." (PMID 25588786, 2015). "Our meta-analysis results reveal a strong link between MMP-7 overexpression and lung cancer progression." (PMID 25588786, 2015). "Our results suggest that fibulin-5 antagonizes Wnt signaling by inhibiting ERK and indirectly activating GSK3β to restrain β-catenin in the cytoplasm, which prevents MMP-7 and c-Myc expression and lung cancer cell invasion and proliferation." (PMID 25909283, 2015). "MMP-7 protein expression in lung cancer with histologic grade 3 to 4 was remarkably higher than histologic grade 1 to 2, which was not influenced by age (Age <60: OR = 1.63, 95% CI = 1.08 to 2.47, P = 0.021; Age ≥ 60: OR = 1.56, 95% CI = 1.02-2.38, P = 0.041)." (PMID 25588786, 2015). "The major findings of the present meta-analysis revealed a significantly higher MMP-7 protein expression in lung cancer patients with TNM stage III-IV compared to patients with TNM stage I-II (OR = 1.82, 95% CI: 1.19-2.78, P = 0.006)." (PMID 25588786, 2015). "Fibulin-5 and fibulin-3 suppress lung cancer invasion and metastasis by inhibiting the expression of matrix metalloproteinase 7 (MMP-7), which promotes tumor metastasis by degrading the basement membrane that serves as a barrier to surrounding tissues." (PMID 25909283, 2015). "When MMP-7 was expressed in human lung cancer or immortalized airway epithelial cells, it enhanced growth and migration." (PMID 23300791, 2012). "The plasma protein levels of MMP-7 in lung cancer patients (median=0.72 ng/mL) were significantly higher than those in healthy control subjects (median=0.30 ng/mL)(P < 0.001)." (PMID 23249718, 2012). "When the cutoff of MMP-7 protein level was set at 0.56 ng/mL, the sensitivity and specificity of detecting lung cancer were 62.3% and 76.0%, respectively." (PMID 23249718, 2012). "Meanwhile the distinct role of Kindlin-1 and Kindlin-2 in the regulation of lung cancer cell invasion was examined by determination of the expression of metalloprotenases including MMP7, MMP9 and MMP13." (PMID 23209705, 2012). "The objectives of this study were to test MMP-7 protein levels in the peripheral blood of lung cancer patients and healthy control subjects and to determine their corresponding clinical significance." (PMID 23249718, 2012). "MMP7 plays a nuanced yet pivotal role in lung cancer progression by targeting NCL at Asp255." (PMID 39304978, 2024). "FBLN5 may slow down the metastasis and invasion of lung cancer by inhibiting MMP-7 expression and promoting tumor metastasis through BM degradation." (PMID 37214471, 2023). "Additionally, we examined these cellulosic derivatives with cytotoxic effects on lung cancer cells (A549) and colon cancer cells (Caco2), and we then examined the levels of β-Catenin, c-Myc, Cyclin D1, and MMP7 gene expression in A549 cells." (PMID 37666882, 2023).
lung cancer (continued). "In A549 and H1299 lung cancer cells, Zbed3 overexpression promoted cancer cell proliferation and invasiveness, as well as Wnt signalling and expression of downstream mediators, including β‐catenin, cyclin D1 and MMP7 (P < 0.05)." (PMID 30417576, 2019). "Fibulin-3 and Fibulin-5 inhibit the invasion and metastasis of lung cancer (LC) cells by downregulating the expression of matrix metalloproteinase 7 (MMP-7), which promotes metastasis through degradation of the basement membrane that acts as barrier to the adjacent tissues." (PMID 30305430, 2018). "Our data supported the notion that the over-expression of miR-329 was associated with the down-regulation of MMP-7 and MMP-9 levels in lung cancer cells (A549 and H1299), which further confirmed the inhibitory role of miR-329 on invasion and migration of NSCLC cells." (PMID 26909600, 2016). "Thus, the MMP-7 overexpression pattern more closely reflects the tumor behavior than the current staging systems, indicating the role of MMP-7 as a potent biomarker for the pathological features of lung cancer." (PMID 25588786, 2015). "MMP-7 overexpression could also regulate the proliferation of lung cancers through activation of EGFR and the production of mature HB-EGF to activate the receptor ErbB4." (PMID 25588786, 2015). "Based on our results, we propose that a MMP-7 specific inhibitor may prevent and treat invasion and metastasis of lung cancer." (PMID 25588786, 2015). "Our meta-analysis results revealed that MMP-7 overexpression is associated with advanced TNM and histological grades, and is linked to aggressive LN metastasis in lung cancer patients; thus MMP-7 is a useful biomarker to assess the disease status in lung cancers." (PMID 25588786, 2015). "Finally, a total of 14 cohort studies, published between 2004 and 2012, provided the necessary information about the correlation of protein expression of MMP-7 with the pathological features of lung cancer." (PMID 25588786, 2015). "Thus, we performed a systematic meta-analysis to evaluate the link between MMP-7 protein expression and the pathological features in lung cancer." (PMID 25588786, 2015). "Since both MMP-7 and c-Myc are downstream effectors of the Wnt/β-catenin pathway, we hypothesized that the function of fibulin-5 in lung cancer is mediated through Wnt/β-catenin signaling." (PMID 25909283, 2015). "In this study, we investigated the correlation between MMP-7 expression and lung cancer pathology." (PMID 25588786, 2015). "Finally, 14 cohort studies satisfied our inclusion/exclusion criteria, and these 14 studies, published between 2004 and 2012, were selected for meta-analysis to understand the influence of MMP-7 expression in lung cancer progression." (PMID 25588786, 2015). "MMP-7 activity related to E-cadherin shedding could drive the accumulation of β-catenin in lung cancers overexpressing MMP-7, leading to the activation of multiple pathways involving dysregulated functions of both extracellular and intracellular components." (PMID 25588786, 2015). "Strikingly, these cultures also express elevated Mmp10 mRNA, but no increase in Mmp2, Mmp7, Mmp9, Mmp11, Mmp12 or Mmp14, other Mmp species commonly linked to lung cancer." (PMID 22545096, 2012). "The plasma protein levels of MMP-7 increase in the peripheral blood of lung cancer patients." (PMID 23249718, 2012). "MMP-7 is an established tumor promoter in colon, prostate, pancreatic, and lung cancers." (PMID 23251453, 2012). "Peripheral blood MMP-7 can be used as a tumor marker for detecting lung cancer." (PMID 23249718, 2012). "Loss- and gain-of-function experiments in human bronchial epithelial and lung carcinoma cell lines revealed that Ascl1, MMP-7 and MGMT are able to protect cells from the tobacco-specific nitrosamine NNK-induced DNA damage and the alkylating agent cisplatin-induced apoptosis." (PMID 23300791, 2012).
lung cancer (continued). "Although Puthenedam’s report showed that MMP7-cleaved galectin-3 inhibited the motility of intestinal epithelial cells, there was no further evidence indicating the phenomena could be applied to lung cancer cells." (PMID 30925742, 2019). "We also found that X-ray irradiation up-regulated Dab2 expression in lung cancer cells with hypermethylated Dab2 gene, which lead to increased Axin expression and subsequently decreased expression of β-catenin, as well as Wnt pathway factors including: cyclin D1, MMP-7 and c-myc in LK cells." (PMID 30547821, 2018). "However, it is unclear how fibulin-5 inhibits MMP-7 expression and lung cancer cell invasion." (PMID 25909283, 2015). "In addition, NKD1 knockdown by siRNA technology could markedly up-regulate Dishevelled-1 and β-catenin protein levels, enhance the transcription of MMP-7 and promote the invasiveness of lung cancer cells." (PMID 21599923, 2011). "In addition, NKD1 knockdown could up-regulate Dishevelled-1 and β-catenin protein levels, as well as increased MMP-7 transcription and the invasive ability of lung cancer cells." (PMID 21599923, 2011). "For example, TMEM196 silencing in lung cancer cells and mice resulted in the upregulation of MMP2 and MMP7." (PMID 37367036, 2023). "Hsa_circ_0006692 modulated EMT of lung cancer cells via the stimulation of CDH1, CDH2, VIMENTIN, and MMP7." (PMID 35627232, 2022). "Further studies are needed to verify association of rs1799750 in MMP-1, rs243865 in MMP-2, rs11568818 in MMP-7, rs2252070 in MMP-13 and rs28366003 in MT2A with breast, colon and lung cancers." (PMID 32765800, 2020). "Similar effect was observed by Sun et al52 who showed that MiR‐329 caused down‐regulation of MET expression what led to decreased mRNA level of MMP‐7 and MMP‐9 and thus reduced cellular migration and invasiveness of lung cancer cells." (PMID 31638339, 2019). "Matrix metalloproteinase 7 (MMP-7) is one of the leading biomarkers in several cancers and has recently generated interest for its potential applications in lung cancer settings." (PMID 25588786, 2015). "A study comparing gene expression in lung tissues by microarray analysis from five patients with both lung cancer and IPF revealed five genes e.g. SMAD4, P21, MT1A, MMP7 and TIMP1; these were down-regulated in cancer tissue in comparison to IPF, in at least two of the patients." (PMID 33905434, 2021). "Next, we evaluated whether the CTNNBIP1 expression was related to changes in the expression of various β-catenin-targeted genes, such as MMP7, cyclin D1, and c-MYC, among these lung cancer patients." (PMID 31766223, 2019). "On the basis of their lung-tumorigenesis promoting functions, the MMP members MMP-1, MMP-2, MMP-7, MMP-9 and MMP-10 may result promising biomarkers for lung cancer." (PMID 29207990, 2017). "Luciferase assay was used to detect expression of MMP-7 reporter construct transfected with or without EFEMP1 in lung cancer cells." (PMID 25676403, 2015). "The main result of our analysis demonstrated a significant association between MMP-7 and TMN stages, histologic grade and LN metastasis of lung cancer but not between MMP-7 and histology." (PMID 25588786, 2015). "The data suggest that RNF146 might regulate the migration and invasion of lung cancers by regulating MMP2 and MMP7." (PMID 24454854, 2014). "MMP7 and MMP12 levels are elevated in lung cancer, which may facilitate breakdown of the extracellular matrix and tumor spread." (PMID 25114662, 2014). "Numerous reports in the literature have evaluated the utility of combined tumor-related markers for lung cancer detection and, consequently, we tested whether MMP-1, MMP-7 and MMP-9 could provide complementary discrimination and improve the performance of MMP-9." (PMID 29207990, 2017).
lung cancer (continued). "Our analysis shows that MMP-7 expression is higher in the III-IV stage than in the I-II stage and is overexpressed to a greater degree in the 1 to 2 histologic grade than in the 3 to 4 histologic grade, suggesting an important role of MMP-7 in the progression of lung cancer." (PMID 25588786, 2015). "A low expression of CTNNBIP1 is correlated with a high level of expression of MMP7, and there is also an upward trend in terms of the pathological stage and poorer patient survival, which suggests that CTNNBIP1 may be able to serve as a prognostic biomarker for lung cancer." (PMID 31766223, 2019). "To test this hypothesis, we examined the expression of MMP-7(a target gene of the canonical Wnt pathway) in NKD1-depleted cells and found that MMP-7 mRNA levels were significantly increased in comparison with lung cancer cells without NKD1 depletion (P < 0.05)." (PMID 21599923, 2011). "Statistically significant higher serum levels were confirmed for MMP-7 (P = 0.014) and MMP-9 (P < 0.001) when comparing lung cancer with non-cancer patients (both healthy and benign)." (PMID 29207990, 2017).
hepatocellular carcinoma (36 papers, 2012 to 2025). A malignant tumor that arises from hepatocytes. "MMP7, another β-catenin target implicated in hepatocellular carcinoma cell migration, may also contribute to SSCs motility." (PMID 40638605, 2025). "Prior studies have demonstrated that TGF-β signaling in hepatocellular carcinoma induces MMP-7 and heparanase, promoting syndecan-1 shedding and enhancing fibrogenic signaling." (PMID 40572724, 2025). "In order to observe the effect of the PI3K/AKT pathway on the expression of MMP7 and the ability of migration and invasion of hepatoma cells, MHCC97H and SMMC-7721 cells were treated with PI3K/AKT inhibitor LY294002 (20 μM) for 24 h." (PMID 36980736, 2023). "Snail, a zinc finger transcription factor, increases cancer invasion by upregulating members of the MMP family, such as MMP-1, MMP-2, and MMP-7, in hepatocellular carcinoma." (PMID 36522523, 2023). "In hepatoma cells, silencing KIF18A reduced the expression of cyclin B1, MMP-9, MMP-7, and Akt-related proteins and inhibited hepatoma cell growth, invasion, and metastasis." (PMID 37965453, 2023). "Another study demonstrated that KIF18A is involved in the proliferation and motility of hepatocellular carcinoma (HCC) cells by regulating the cell cycle and signaling pathways linked to MMP-7/9." (PMID 35464837, 2022). "In this regard, a study in hepatocellular carcinomas demonstrated the inhibition of cell migration and invasion after diminishing MMP7." (PMID 34233687, 2021). "Given the critical roles of matrix metalloproteinases (MMPs) in the migration and metastasis of tumour cells, the levels of MMP-2 and MMP-7 were examined after exposure to protopine in liver carcinoma cells." (PMID 34315493, 2021). "Supporting our results, other studies have revealed that WTAP promotes tumor cell proliferation in hepatocellular carcinoma, and increases the migration and invasion of cholangiocarcinoma cells by upregulating MMP7." (PMID 28212562, 2017). "Furthermore, the transcriptional activation of MMP7 by the FOSB-MAFG transcription factor complex was demonstrated to be critical for the malignant progression in hepatocellular carcinoma." (PMID 39164746, 2024). "The RGD-dependent inhibition of MMP-7 by FBLN5 may contribute to the development of new therapeutic strategies against hepatocellular carcinoma." (PMID 36672502, 2023). "MRPS31 suppression enhanced hepatoma cell invasiveness by augmenting MMP7 and COL1A1 expression." (PMID 34772924, 2021). "KIF18A also promotes invasion and metastasis of hepatoma cells via MMP-7/MMP-9-related pathway." (PMID 30813560, 2019). "And FGF1 induced FGFR phosphorylation to activate PI3K and JNK, resulting in the activation of MMP7 and MMP6 in hepatocellular carcinoma, which might be the underlying mechanism in the hepatocellular carcinoma metastasis." (PMID 26183397, 2015). "Several hepatocellular carcinoma (HCC) cell lines display a low expression of fibulin-5, and suggest that fibulin-5 may inhibit HCC invasion and metastasis by suppressing the MMP-7 expression." (PMID 34063320, 2021). "In previous several studies, KIF18A was known to be associated with signalling pathways including Akt and metastasis‐related proteins (MMP‐7 and MMP‐9) in hepatoma cells and involved in Akt signalling pathways during human breast carcinogenesis." (PMID 32253833, 2020). "This idea is supported by the findings that reduced expression of FBLN5 correlates with poor prognostic features in hepatocellular carcinoma, and FBLN5 negatively regulates MMP-7 in these cells." (PMID 29581841, 2018). "The expression of cell cycle-related protein (cyclin B1), invasion and metastasis-related proteins (MMP-7 and MMP-9) and Akt-related proteins in hepatoma cells was also decreased after knocking down KIF18A." (PMID 29466986, 2018).
hepatocellular carcinoma (continued). "By knocking down the expression of KIF18A in hepatoma cells, we detected biological behavioural changes of HCC cells and explored the correlation between KIF18A and some signalling pathway-related proteins (Akt, Aurora A, cyclin B1, MMP-7, etc.)." (PMID 29466986, 2018). "Meanwhile, the endogenous expression of TGFβ1 was tightly mediated by MMP-7, thus constituting an MMP-7/syndecan-1/TGFβ1 autocrine loop to mediate hepatocellular carcinoma (HCC) metastasis." (PMID 31822964, 2020). "In hepatocellular carcinoma (HCC), upregulation of the EMT-TF Snail not only repressed E-cadherin transcription but also increased expression of MMP-1, MMP-2, MMP-7, and MT1-MMP leading to accelerated invasion." (PMID 31540068, 2019).
idiopathic pulmonary fibrosis (36 papers, 2011 to 2026). Idiopathic pulmonary fibrosis (IPF) is a nonneoplastic pulmonary disease that is characterized by the formation of scar tissue within the lungs in the absence of any known cause. "Studies on certain molecules, particularly matrix metalloproteinases (such as MMP-7 and MMP-1) and Krebs von den Lungen-6 (KL-6), suggest that these molecules could be used as biomarkers in idiopathic pulmonary fibrosis (IPF) in the near future." (PMID 39597967, 2024).